USP42 (ubiquitin specific peptidase 42)
Description:
Deubiquitinating enzyme which may play an important role during spermatogenesis.
Synonyms: FLJ12697
Tractability: PROTAC: ubiquitination databases record sites on it; its protein half-life has been measured.
Gene: Protein-coding gene on chromosome 7 (6,104,934 to 6,161,565, forward strand). Ensembl gene ENSG00000106346.
Subcellular location (Human Protein Atlas): Nucleoplasm; Nucleoli
Pathways (Reactome):
Metabolism of proteins: Ub-specific processing proteases
Gene Ontology:
Molecular function: cysteine-type deubiquitinase activity; protein binding
Biological process: protein deubiquitination; regulation of apoptotic process
Cellular component: nucleoplasm
Genetic constraint (gnomAD): Loss-of-function variants: 21 observed, 84.73 expected, observed/expected ratio (o/e) 0.25, 90% interval 0.17 to 0.36. The synonymous counts are far from expectation, so gnomAD's model fits this gene poorly and the ratio says little. Missense variants: 2,116 observed, 1,656.2 expected, observed/expected ratio (o/e) 1.28, 90% interval 1.23 to 1.32. Synonymous variants: 909 observed, 659.11 expected, observed/expected ratio (o/e) 1.38, 90% interval 1.3 to 1.46.
Homologues: Orthologues: chimpanzee USP42 (99% identical), macaque USP42 (96% identical), dog USP42 (78% identical), pig USP42 (74% identical), rabbit USP42 (72% identical), rat Usp42 (70% identical), mouse Usp42 (69% identical), tropical clawed frog usp42 (36% identical), zebrafish usp42 (34% identical). Paralogues in human: USP36 (28% identical), USP17L20 (18% identical), USP17L24 (18% identical), USP17L25 (18% identical), USP17L26 (18% identical), USP17L27 (18% identical), USP17L28 (18% identical), USP17L29 (18% identical), USP17L30 (18% identical), USP17L11 (18% identical), USP17L12 (18% identical), USP17L18 (18% identical), and 59 more.
Diseases named in the same sentence as USP42 in open-access papers:
USP42 is named in the same sentence as 25 diseases in open-access papers, as found by Europe PMC text mining. Sharing a sentence is not in itself a finding about the gene and the disease. The quoted sentences say what the papers report.
leukemia (3 papers, 2013 to 2023). A malignant (clonal) hematologic disorder, involving hematopoietic stem cells and characterized by the presence of primitive or atypical myeloid or lymphoid cells in the bone marrow and the blood. "Genes USP42 and RUNX1 are both studied in leukemia for their involvement in chromosomal translocations." (PMID 37628680, 2023).
gastric cancer (2 papers, 2016 to 2024). A primary or metastatic malignant neoplasm involving the stomach. "Comparison of various gastric cancer cell lines revealed that the expression level of USP42 protein in AGS and MKN-45 cells is higher than that of SGC-7901, BGC-823 and MKN-28 cells." (PMID 27030989, 2016). "Correlation of USP42 expression with patients’ features in gastric cancer." (PMID 27030989, 2016). "However, there are few studies on the expression and biological function of USP42 in gastric cancer (GC)." (PMID 27030989, 2016).
lymph node metastasis (2 papers, 2016 to 2021). "Moreover, USP42 expression was associated with tumor size, TNM stage, lymph node metastasis and overall survival of GC patients." (PMID 27030989, 2016). "USP42 expression was significantly correlated with tumor size, TNM stage, lymph node metastasis and overall survival of patients with GC." (PMID 27030989, 2016). "Expression of ubiquitin-specific protease 42 (USP42) mRNA was demonstrated to be higher in GC than in nontumorous tissues, and correlated with tumor size, TNM stage, lymph node metastasis, and OS of patients with GC." (PMID 34830815, 2021).
colon cancer (1 paper, 2025). "Additionally, CNV analysis indicated a significant increase in the proportion of CNVs for CHRNA4 and USP42 in colon cancer, while an increase in CNVs for FURIN and FES was noted in rectal cancer." (PMID 40426913, 2025).
dengue (1 paper, 2019). "To dissect the cause of USP42 downregulation upon dengue NS5 overexpression, we checked whether USP42 gene sequence has strong binding sites for any relevant microRNA." (PMID 32123831, 2019). "Our results demonstrated that dengue viral infection as well as dengue NS5 overexpression were able to downregulate the endogenous USP42 expression level in human microglial cells." (PMID 32123831, 2019). "We used different doses of dengue NS5 plasmids for transfection to establish the cause and effect relationship of NS5 protein over USP42 expression level." (PMID 32123831, 2019). "Since dengue NS5 is known to localize in the nucleus and influence the host transcription/splicing machinery, we investigated the functional implication of modulation of USP42." (PMID 32123831, 2019). "We could observe a specific USP42 downregulation in case of dengue NS5 overexpression but not in case of dengue NS1 overexpression." (PMID 32123831, 2019).
hepatocellular carcinoma (1 paper, 2025). A malignant tumor that arises from hepatocytes. "Interestingly, when we analyzed the USP42 expression using hepatocellular carcinoma (HCC) cDNA chip from 26 human samples, we found that USP42 was highly expressed in the tumor area compared to that in the adjacent tissue." (PMID 40091484, 2025).
lung adenocarcinoma (1 paper, 2021). A carcinoma that arises from the lung and is characterized by the presence of malignant glandular epithelial cells. "In addition, we analyzed USP42 and PLRG1 expression in the TCGA dataset and found significant upregulation of USP42 and PLRG1 in lung adenocarcinoma and squamous carcinoma." (PMID 33731873, 2021).
lung carcinoma (1 paper, 2021). "The protein levels of USP42 in surgically collected lung cancer and adjacent normal tissue pairs from six patients were assessed, and the results showed elevated expression of USP42 in cancer specimens relative to normal tissues." (PMID 33731873, 2021). "USP42 governs the phase separation of the spliceosome component PLRG1 to regulate a range of mRNA splicing events that are linked to diverse cellular functions and the clinical prognosis of lung cancer patients." (PMID 33731873, 2021). "Strikingly, increased expression of USP42 or PLRG1 negatively correlated with patient survival, thus indicating a tumour-promoting role for both USP42 and PLRG1 in human lung cancer." (PMID 33731873, 2021). "To explore the clinical relevance of USP42 and PLRG1 expression in lung cancer, we analyzed the overall survival of cancer patients using datasets from GSE11969 and GSE31210." (PMID 33731873, 2021).
non-small cell lung carcinoma (1 paper, 2021). A group of at least three distinct histological types of lung cancer, including non-small cell squamous cell carcinoma, adenocarcinoma, and large cell carcinoma. "Finally, USP42 expression is strongly correlated with that of PLRG1 in non-small-cell lung cancer samples and predicts adverse prognosis in overall survival." (PMID 33731873, 2021).
Parkinson disease (1 paper, 2024). A progressive degenerative disorder of the central nervous system characterized by loss of dopamine producing neurons in the substantia nigra and the presence of Lewy bodies in the substantia nigra and locus coeruleus. "The differentially methylated bb-CpG cg11725581 in Parkinson’s Disease dataset is mapped between the AIMP2 and USP42 genes." (PMID 39060467, 2024).
prostate carcinoma (1 paper, 2025). A carcinoma that arises from epithelial cells of the prostate gland. "Pharmacological co-targeting of USP42 may overcome olaparib resistance, thereby expanding the therapeutic applicability of PARP inhibition in prostate cancer patients." (PMID 40718793, 2025).
prostate tumor (1 paper, 2025). "Compared with normal cells, USP42 expression was elevated in prostate tumor cells." (PMID 40718793, 2025).
thyroid cancer (1 paper, 2024). "Our in silico results support that USPs, other than USP42, are altered in sporadic thyroid cancer, and that USPs can be in line with other mutations associated with thyroid cancer development, such as BRAF p.(Val600Glu)." (PMID 38338801, 2024).
viral infection (1 paper, 2019). "The role of USP42 or what might regulate USP42 expression levels/activity in case of viral infection has not been investigated at all." (PMID 32123831, 2019).
tumor (12 papers, 2016 to 2025). "USP42 is highly expressed in GC tissue and conspicuously associated with the tumor size, TNM staging, lymph node metastasis, and OS rate of GC patients, while inhibition of USP42 can induce G0/G1 block and suppress cell proliferation and invasion." (PMID 33791299, 2021). "USP42 was significantly associated with tumor size (P = 0.0328), TNM stage (P = 0.0059) and lymph node metastasis (P = 0.0184)." (PMID 27030989, 2016). "Thus, our data indicated that elevated expression of USP42 in GC may promote tumor metastasis and is associated with the clinical outcome of GC patients." (PMID 27030989, 2016). "Further experiments revealed that targeting USP42 induced DNA damage in PCa cells and suppressed tumor growth both in vivo and in vitro." (PMID 40718793, 2025). "Tumors were significantly larger and heavier in the control group than in the USP42-knockdown group, indicating that suppression of USP42 significantly inhibited PCa tumor growth in vivo." (PMID 40718793, 2025). "Immunohistochemical analysis of PCa samples was used to evaluate USP42 expression in normal and tumor tissues." (PMID 40718793, 2025). "Using immunohistochemistry (IHC) we noted that, although USP42 was expressed in the normal tissue, an increased expression was observed in the tumor specimens, indicating overexpression." (PMID 38338801, 2024). "In gastric cancers, USP42 was found upregulated and the staining intensity correlated with the tumor size and aggressiveness (staging, lymph node metastasis and the overall survival of patients)." (PMID 34577547, 2021). "The USP42-suppressed cells exhibited significantly less invasive potential than the siNC-transfected cells (P<0.01), suggesting that high expression of USP42 enhanced tumor invasiveness." (PMID 27030989, 2016). "The tumor growth rate of mice injected with USP42-siRNA was significantly slower than that of mice injected with control siRNA." (PMID 27030989, 2016). "Moreover, USP42 knockdown markedly enhanced the tumor-suppressive effects of olaparib when used in combination." (PMID 40718793, 2025). "Furthermore, we assessed USP42 expression levels in both normal and tumor-derived prostate cell lines." (PMID 40718793, 2025). "The increased USP42 expression might be important for tumor progression and metastasis of GC, and can serve as a prognostic marker for this disease." (PMID 27030989, 2016). "In conclusion, USP42 overexpression could be a potential prognostic marker for GC, regulate the survival and invasive properties of GC, and may represent a novel therapeutic molecular target for this tumor." (PMID 27030989, 2016). "We observed that reducing USP42 levels led to DDR abnormalities, resulting in DNA damage, and inhibited tumor cell proliferation." (PMID 40718793, 2025). "Depletion of several ubiquitinases and proteasome components (DTX3L, UBE2E1, RNF31, RNF115, USP2, USP42, PSMC3, and PSMD10) were also found to inhibit tumor cell migration." (PMID 31278301, 2019). "The effects of USP42 inhibition on PCa cell proliferation were assessed both in vitro and in vivo through MTT assays, colony-formation assays, and a subcutaneous xenograft tumor model in nude mice." (PMID 40718793, 2025).
cancer (8 papers, 2016 to 2025). A tumor composed of atypical neoplastic, often pleomorphic cells that invade other tissues. "Subsequent validation of splicing changes in nine newly identified targets that were arbitrarily chosen to include cancer-associated genes confirmed the impact of USP42 regulation on endogenous AS events." (PMID 33731873, 2021). "Thus, loss of USP42 confers cancer cell EMT characteristics and hypersensitivity to WNT signalling, a finding paralleled by experiments on mouse intestinal organoids." (PMID 33938624, 2021). "Taken together, these results indicate potential roles of USP42 in cancer progression by regulating AS of cancer-related genes." (PMID 33731873, 2021). "Functionally, USP42 downregulation deregulates multiple mRNA splicing events and leads to deterred cancer cell growth, which is consistent with the impact of PLRG1 repression." (PMID 33731873, 2021). "As a cysteine protease, USP42 holds the potential to serve as a therapeutic target in cancer treatment." (PMID 33731873, 2021). "We then applied RNAi technology, which is widely used in cancer research or cancer therapy, to knocking down USP42 expression in two GC cell lines." (PMID 27030989, 2016). "Next, we tried to explore the underlying mechanisms by evaluating the expression of MMPs and EMT regulators in USP42-suppressed cancer cells." (PMID 27030989, 2016). "Lowering USP42 expression effectively decreased cancer cell proliferation in vitro and in vivo." (PMID 27030989, 2016).
USP42 also shares sentences with these, for which no sentence is quoted: acute myeloid leukemia (2 papers); anemia (1); breast carcinoma (1); colorectal cancer (1); head and neck cancer (1); liver cancer (1); myeloid malignancies (1); rectal cancer (1); squamous carcinoma (1).